PCDHA2 (protocadherin alpha 2)
Description:
Potential calcium-dependent cell-adhesion protein. May be involved in the establishment and maintenance of specific neuronal connections in the brain.
Synonyms: PCDH-ALPHA2
Tractability: Antibody: its Gene Ontology location is reachable by antibodies, with high confidence; UniProt places it where antibodies can reach, with medium confidence; UniProt predicts a signal peptide or a membrane-spanning region.
Gene: Protein-coding gene on chromosome 5 (140,794,852 to 141,012,347, forward strand). Ensembl gene ENSG00000204969.
Subcellular location: Cell membrane
Subcellular location (Human Protein Atlas): Microtubules; Cytokinetic bridge; Mitotic spindle; Primary cilium
Gene Ontology:
Molecular function: protein binding; cell adhesion molecule binding; calcium ion binding
Biological process: cell adhesion; nervous system development; homophilic cell-cell adhesion
Cellular component: plasma membrane; endoplasmic reticulum; membrane; nucleus
Genetic constraint (gnomAD): Loss-of-function variants: 58 observed, 68.48 expected, observed/expected ratio (o/e) 0.85, 90% interval 0.69 to 1.05. The upper end of that interval is the gene's LOEUF score, 1.05, which puts it in group 4 of 6, group 1 being the genes least tolerant of losing a copy. Missense variants: 1,267 observed, 1,315.2 expected, observed/expected ratio (o/e) 0.96, 90% interval 0.92 to 1.01. Synonymous variants: 634 observed, 588.61 expected, observed/expected ratio (o/e) 1.08, 90% interval 1.01 to 1.15.
Homologues: Orthologues: mouse Pcdha2 (87% identical). Paralogues in human: PCDHA1 (83% identical), PCDHA3 (83% identical), PCDHA4 (83% identical), PCDHA13 (82% identical), PCDHA11 (81% identical), PCDHA6 (81% identical), PCDHA5 (81% identical), PCDHA7 (80% identical), PCDHA12 (80% identical), PCDHA9 (80% identical), PCDHA10 (80% identical), PCDHA8 (80% identical), and 49 more.
Diseases named in the same sentence as PCDHA2 in open-access papers:
PCDHA2 is named in the same sentence as 6 diseases in open-access papers, as found by Europe PMC text mining. Sharing a sentence is not in itself a finding about the gene and the disease. The quoted sentences say what the papers report.
colon cancer (1 paper, 2023). "Interestingly, four genes that were originally highly expressed in the high SOCS3 expression group in colon cancer became low expressed after lung metastasis, including TTC40, PCDHA2, SP3P and ZNF471." (PMID 37025997, 2023).
depression (1 paper, 2026). "The present study provided genetic evidence supporting the causal role of DNAm in the onset of depression or PTSD after injury and identified DLGAP2, ERICH1, PCDHA2, and PTPRN2 as the candidate genes worthy of further exploratory investigation." (PMID 41995537, 2026). "Our results showed significant causal genetic evidence for injury-associated DNAm changes at cg24526596 (DLGAP2), cg00157656 (ERICH1), cg12317217 (PCDHA2), and cg12661624 (PTPRN2) on depression onset." (PMID 41995537, 2026).
gastric adenocarcinoma (1 paper, 2019). "Mutations in another gene from the protocadherin alpha cluster, PCDHA2, were also associated with adverse outcomes in gastric adenocarcinoma (STAD: HR, 1.604; 95% CI 1.061–2.427; P = 0.025)." (PMID 31036064, 2019). "Mutations in another cadherin gene PCDHA2 when considered alongside signature 2 were also associated with survival in gastric adenocarcinoma (P < 0.001)." (PMID 31036064, 2019).
schizophrenia (1 paper, 2021). A major psychotic disorder characterized by abnormalities in the perception or expression of reality. "We found that schizophrenia-associated members of the clustered protocadherin family PCDHA2, PCDHA3 and PCDHA5 were downregulated by MIA and mapped to the cell adhesion biological processes." (PMID 34859219, 2021). "Subsequently, we tested the effects of HSV-1 infection on the expression of schizophrenia-associated protocadherins PCDHA2, PCDHA3 and PCDHA5 given their identification in cell adhesion biological processes in our earlier analysis." (PMID 34859219, 2021). "Additionally, we showed that schizophrenia-associated protocadherins PCDHA2, PCDHA3 and PCDHA5 were downregulated in a dose-dependent manner in neuronal precursor cells following HSV infection." (PMID 34859219, 2021).
PCDHA2 also shares sentences with these, for which no sentence is quoted: tumor (2 papers); autism (1).